IDH1 (isocitrate dehydrogenase (NADP(+)) 1)
Diseases named in the same sentence as IDH1 in open-access papers (continued):
Sharing a sentence is not in itself a finding about the gene and the disease.
tumor (continued). "In this respect, it is interesting to note that the percentage of non-R132H IDH1/2-mutated tumours was almost two-fold lower in TAVAREC trial samples (13%) compared to CATNON (19%) and TCGA (20%)." (PMID 33740099, 2021). "ctDNA levels were assessed in 83 of the remaining 104 patients, whose tumours harboured a hotspot mutation in IDH1/2 or GNAS." (PMID 34528398, 2021). "A heatmap of most differentially methylated probes shows that non-R132H IDH1/2-mutated tumours and tumours assigned to the prognostically poorer subclass A_IDH_HG clustered at opposite ends of this heatmap." (PMID 33740099, 2021). "Elevated d-2-HG levels are considered a biomarker of tumor-associated IDH1/2 mutations and d-2-HGA1,2." (PMID 34876568, 2021). "Similar to results observed on Cry1 expression, IDH1 mutated U-87MG cells showed lower levels of Cry2 than wild-type cells with implications in tumor proliferation." (PMID 34361055, 2021). "We used genome-wide DNA methylation data from CATNON trial samples and compared profiles of IDH1R132H mutated tumours (n = 369) to those harbouring other “non-R132H” IDH1 and IDH2 hotspot mutations (n = 69)." (PMID 33740099, 2021). "Patients harbouring IDH1R132H mutated tumours have lower levels of genome-wide DNA-methylation, and an associated increased gene expression, compared to tumours with other IDH1/2 mutations (“non-R132H IDH1/2 mutations”)." (PMID 33740099, 2021). "QQ-based OEF mapping with CAT performed markedly better in prediction of IDH1 mutation status than WHO tumor grade in this study cohort." (PMID 34671241, 2021). "Information collected from each patient included sex, age, tumor grade, isocitrate dehydrogenase 1 (IDH1) mutation status, peritumoral brain edema volume, tumor volume, and ALPS index." (PMID 34631582, 2021). "We recruited 145 patients, and ctDNA levels were assessed in patients with tumours carrying IDH1/2 or GNAS mutations." (PMID 34528398, 2021). "Survival correlated with tumour grade, and detection of IDH1, IDH2 and GNAS mutations in plasma pre‐ and postoperatively." (PMID 34528398, 2021). "Specific tumor-related biomarkers were recorded; a total of 104 (52.8%) patients had ki-67 index <30%, while 31 patients were tested as IDH-1 mutation." (PMID 34476009, 2021). "Each tumor included in the study contained a large population of cells with confirmed IDH1 or IDH2 mutations and co-deletion of chromosome 1p and 19q arms, as well as tumor-specific CNVs." (PMID 34948008, 2021). "Expression level of H19 was significantly correlated with tumor grade and IDH1(R132) mutation status (p < 0.05)." (PMID 34081618, 2021). "Although this difference in frequency was not significant, these numbers are in line with the notion that non-R132H IDH1/2-mutated tumours have lower frequencies of malignant progression." (PMID 33740099, 2021). "Tumour tissue from forty-five patients were comprehensively analysed for IDH1 or IDH2 mutations and methylation of sixteen sites (CpG’s 74–89) in the CpG island of the MGMT gene." (PMID 34209555, 2021). "Mutations in ARID1A, ARID2, BRAF, SMARCA4, TERT and IDH1 were significantly exclusive to intracranial metastases while the same variants remained undetected in the corresponding extracranial tumor tissues." (PMID 33578810, 2021). "We aimed to investigate the correlations of glymphatic function with the volumes of tumor and peritumoral brain edema, tumor grades, and isocitrate dehydrogenase 1 (IDH1) mutation status." (PMID 34631582, 2021).
tumor (continued). "It was found that the global levels of H3K79 dimethylation (H3K79me2) were abnormally increased in IDH1/2-mutated tumor cells due to the overexpression of DOT1L." (PMID 34425876, 2021). "In vivo, in a human IDH1-mutated tumor xenograft model it showed potent activity in lowering tumor levels of R-2-HG, good pharmacokinetics properties and was well tolerated." (PMID 33898313, 2021). "Next, we assessed the relationship between the Neural G0 eigengene and patient survival using a Cox proportional hazards regression model that included the covariates tumor grade and IDH1/2 mutation status." (PMID 34101353, 2021). "The D/L-2HG ratio was significantly higher in patients with an IDH1-mutated tumor compared to patients with an IDH1 wild-type tumor; 20.6 (95% confidence interval [CI] 8.6–32.5) versus 1.83 (95% CI 1.4–2.2; p < 0.0001)." (PMID 34069550, 2021). "A mutation-specificity score that incorporates the duration and level of vaccine-induced IDH1(R132H)-specific T cell responses was associated with intratumoral presentation of the IDH1(R132H) neoantigen in pre-treatment tumour tissue." (PMID 33762734, 2021). "IDH-1 mutated tumors present frequently with a unilateral pattern of growth, sharply defined tumor margins, homogeneous signal intensity, and less contrast enhancement on MRI." (PMID 33868245, 2021). "Our data shows that the overall level of DNA methylation was significantly lower in tumours harbouring IDH1R132H mutations compared to tumours harbouring non-IDH1R132H IDH1/2-mutations." (PMID 33740099, 2021). "Comparisons of the ALPS index according to sex, tumor grade, and IDH1 mutation status with age adjustment." (PMID 34631582, 2021). "By utilization of digital droplet PCR on plasma samples, we were able to detect tumor-specific IDH1 hotspot mutations in circulating tumor DNA (ctDNA) in investigated patients." (PMID 34069550, 2021). "Cytogenetic study of the tumor cells confirmed GBM IDH1 wild type with TERT mutation and EGFR amplification." (PMID 33391387, 2020). "On the one hand, mutant IDH1 ceases genetic instability of a tumor, on the other hand, some mutations in the IDH1 gene are known to upregulate DNA repair through epigenetic mechanisms and thus increase cells’ resistance therapy." (PMID 32731436, 2020). "2-Hydroxyglutarate or 2-HG is an oncometabolite produced to strikingly high levels by tumours harbouring somatic isocitrate dehydrogenase mutations (IDH-1 or IDH-2), such that it can be detected in the peripheral blood of patients." (PMID 31819180, 2020). "The autophagy risk signature, IDH1 mutation, and tumor grade factors were adjusted and checked to be independent indices for prognosis prediction." (PMID 32964017, 2020). "These promising in vitro results encouraged us to further understand the role of IDH1 mutation in tumor maintenance." (PMID 31935911, 2020). "Some preliminary studies were performed to study tumor with IDH1 mutations resorting to hyperpolarized 13C MRS." (PMID 32993063, 2020). "Univariate Cox regression model revealed that patients’ clinical characteristics such as age and tumor stage, IDH1 status was associated with their survival as well as CASC2, miR-21, and combined CASC2/miR-21 expression." (PMID 33120918, 2020). "In multivariate regression analysis, reference parameters, such as gender, age, tumor size, recurrence, and IDH1 mutation were used." (PMID 32349342, 2020). "Univariate analysis demonstrated that age, histological type, isocitrate dehydrogenase 1 (IDH1) mutation, neoplasm histologic grade, radiation therapy, and risk score were significant prognostic factors." (PMID 32802843, 2020).
tumor (continued). "It significantly associates with poor prognostic variables including IDH1 negativity, high apoptotic and proliferative indices and depends on tumor’s histopathologic entity more than its grade." (PMID 32856872, 2020). "Peak height was reminiscent of that observed in the surgical tumor samples positive for IDH1 mutation, suggesting expression to be at relevant physiological levels." (PMID 32946483, 2020). "Another recent breakthrough has been reported in CCA patients whose tumours harboured isocitrate dehydrogenase 1 (IDH1) mutations." (PMID 32932925, 2020). "While ACKR3 expression in tumor-associated vessels in IDH1-wildtype tumors predicted a better prognosis, it has reverse consequences in IDH mutated tumors." (PMID 32456359, 2020). "The 2016 update of the WHO Classification of Tumours of the Central Nervous System highlighted molecular parameters as paramount features for the diagnosis, namely IDH1/2 mutations that distinguish primary and secondary GBM." (PMID 32823572, 2020). "The findings suggest a higher incidence of mutant allele–specific imbalance of the KRAS, EGFR, or PIK3A mutations or presence of subclonal tumor populations harboring IDH1/2 mutations." (PMID 32333643, 2020). "The role of IDH1 mutation in oncogenesis has been suggested to be caused by the involvement of this mutation in the inactivation of tumor suppressor genes through promoter hypermethylation." (PMID 32856857, 2020). "IDH1 mutations caused down-regulation of leukocyte chemotaxis, resulting in repression of the tumor-associated immune system." (PMID 32003759, 2020). "Peptide vaccination targeting the IDH1 R132H mutation results in an effective anti-tumor immune response, and suppresses the growth of pre-established IDH1 R132H-mutated tumors." (PMID 32825279, 2020). "MiR-181d level was significantly higher in GBM tumor tissues of patients with a IDH1 R132H variant, which is primarily found in secondary GBMs, compared to miR-181d levels of GBM patients with a IDH1 wild type (p < 0.001)." (PMID 33050332, 2020). "Good concordance (92%) for IDH1 mutation identification between tumour tissue and ctDNA was also reported in the ClarIDHy phase III trial, exploring the role of ivosidenib in IDH1-mutant iCCA." (PMID 32899345, 2020). "The distribution of tumor grades and IDH1 mutation states in subtype C2 was intermediate between subtypes C1 and C3." (PMID 33425739, 2020). "IDH1 was predicted to be mutated in each patient-matched tumor pair of the A2 to G4 progression group." (PMID 32604718, 2020). "The presence of IDH1 mutation is the most common factor used to classify tumor subtypes in terms of disparate molecular pathogenesis and favorable prognosis." (PMID 32335823, 2020). "Nevertheless, these values demonstrate significant potential, and a mean balanced accuracy of 82.9% indicates synchrotron-based transmission FTIR is capable of identifying mutated and wildtype IDH1 tumours." (PMID 33302429, 2020). "Typically, this is achieved by detection of tumor-specific biomarkers, such as mutations like IDH1-R132H in GBM." (PMID 32650387, 2020). "TOXlow tumours are associated with the loss of PTEN and amplification of EGFR, while TOXhigh tumours harbor frequent mutations in IDH1 (91%)." (PMID 32762688, 2020). "Considering the association between gene mutations and SST2 expression, a high level of SST2 expression can be deemed a strong alternative to favorable prognostic markers, such as IDH1 mutation or tumor grade." (PMID 32335823, 2020). "IDH1 mutation status is the genetic alteration with the most significant impact on the updated 2016 edition of the WHO Classification of Tumours of the CNS." (PMID 32382870, 2020). "This separation according to the mutational status of IDH1 is expected and further underlines the quality of our analyzed tumor material." (PMID 32604718, 2020). "This is in accordance with previous reports, which also showed a higher proportion of frontal lobe tumor location in patients with IDH1 mutation." (PMID 32856857, 2020).
tumor (continued). "In this case, the IDH1 mutation is likely a secondary change after the accelerated growth of tumor cells and hypoxia." (PMID 32069381, 2020). "The baseline sPD-L1 levels were significantly associated with tumor grade, IDH-1 mutation status and Ki-67 expression." (PMID 33224142, 2020). "In this study, changes in sPD-L1 levels, IDH-1 mutational status and tumor location were independent prognostic factors (P = 0.003, HR = 0.019, 95% CI: 0.001–0.268; P = 0.011, HR = 0.029, 95% CI: 0.002–0.448; P = 0.002, HR = 26.302, 95% CI: 3.239–213.550)." (PMID 33224142, 2020). "Spearman correlation analysis showed that the baseline sPD-L1 level was positively associated with tumor grade (r = 0.495, P < 0.001), IDH-1 mutational status (r = 0.379, P = 0.016), and Ki-67 expression rate (r = 0.434, P = 0.003)." (PMID 33224142, 2020). "For example, cancer cells with the IDH1 R132H variant present a tumor-specific CD4+ T cell neoepitope." (PMID 32825279, 2020). "The prolonged survival of patients with IDH1 mutations has previously been proposed to be associated with less aggressive biological behavior from the perspective of MRI tumor heterogeneity." (PMID 33121211, 2020). "The variables selected as significant after univariate analysis were the CHI3L1 and OPN expression levels in patient serum, tumor IDH1 mutational status, patient age, and malignancy grade." (PMID 33227903, 2020). "Another study showed that IDH1 mutations in intrahepatic CC were associated with favorable prognosis, smaller tumor size, lower serum CA19-9 levels, and lower TNM stage." (PMID 33014795, 2020). "The heterozygosity of all known IDH1/2 mutations paired with the understanding that these enzymes function as dimers suggest that tumor cells remain dependent on a wild type allele of IDH to catalyze the standard reaction found within the TCA cycle." (PMID 31105869, 2019). "The results contribute to a better understanding of the mechanism of D-2-HG accumulation in tumours with IDH1/2 mutations." (PMID 31092874, 2019). "This table details the tumor diagnosis, location, 1p/19q co-deletion, and IDH1 mutation status, as well as the presence of GPIHBP1." (PMID 31169500, 2019). "Our results confirmed that overexpression of the PSAT1 gene correlates with IDH1 mutations, a lower tumor grade, and a better outcome in LGGs in the CGGA dataset." (PMID 31861486, 2019). "After adjusting for sex, tumor grade, age group, and IDH1 mutation status, the median survival of all patients with PTPμ low was about half as long, 18.6 months, as those with PTPμ high staining, where the median survival was 38.2 months." (PMID 31091655, 2019). "In IDH1 mutated cells the increased levels of 2-HG produce inhibition of dioxygenase function, epigenetic instability and tumor progression." (PMID 31234353, 2019). "We summarize recent findings characterizing molecular mechanisms underlying oncogenic alterations associated with mutated IDH1/2, and their impact on tumor microenvironment and antitumor immunity." (PMID 30857299, 2019). "Examination of other tumor types has revealed a role for IDH1/2 variants in the development of these cancers as well." (PMID 31217899, 2019). "A recent review, reinforces the connection between G-CIMP-high tumours and mutations in IDH1 and the favourable prognoses associated with this subtype." (PMID 31710622, 2019). "In this sense, EVs derived from CSF allowed the detection of IDH1 mutations in five out of eight patients using BEAMing and ddPCR techniques with matched corresponding IDH1 mutations in tumor tissue." (PMID 31284524, 2019). "KRAS/NRAS mutations are common in ICC tumours and 6–32% of patients also have isocitrate dehydrogenase 1 and 2 (IDH1 and IDH2) gene mutations associated with metabolic changes." (PMID 31795195, 2019). "Our results present a novel role of tumor-derived IDH1 mutation and oncometabolite 2-HG in ferroptosis." (PMID 31591388, 2019).
tumor (continued). "Patient age and tumor volume can be used as indicators of IDH1 mutation status in patients with GBM, with high diagnostic performance for simple evaluations in clinical practice." (PMID 31275753, 2019). "Continuous seeding of tumor seeds will further promote the development of tumors, and IDH1/2 mutations play an important role in this process." (PMID 31263678, 2019). "Deletion of the mutant IDH1 allele in IDH1 heterozygous tumor cells or pharmacological inhibition of mutant IDH1 to produce the oncometabolite D-2-hydroxyglutarate (D-2-HG) confers resistance to erastin-induced ferroptosis." (PMID 31591388, 2019). "Consecutive histological sections of four tumors covering the entire en bloc-removed tumor were immunostained with antibodies against IDH1-mutated protein (tumor cells), Ki67 (proliferating cells), and CD34 (blood vessels)." (PMID 30109401, 2019). "Curve fitting analysis of the tumor size compared with the IDH1 mutation status revealed that the probability of an IDH1-mutant status in a GBM patient gradually increased with an increase in the tumor volume." (PMID 31275753, 2019). "Of the 479 LGG tumor samples, 134 (28%) contain mutations in both IDH1 and MUC6, while 5 (1.5%) of 333 normal tissue samples contain a mutation in both these genes." (PMID 30700767, 2019). "Patients harboring an IDH1-mutated tumor seem to present better treatment responses than non-IDH1 patients." (PMID 30708988, 2019). "The IDH1/2 mutations can upregulate VEGF to promote tumor microvessel formation by inhibiting the breakdown of HIF-1α." (PMID 31263678, 2019). "Variants in these genes and IDH1 exhibited an allele frequency that remained stable across all tumor samples." (PMID 31217899, 2019). "By contrast, for oncogenes (orange) with variants highly concentrated at hotspots, particularly KRAS, BRAF, IDH1, the probability of encountering new variants in future tumor samples tends to be low." (PMID 31796730, 2019). "ctDNA mutations in IDH1/2 were shared in all matched ctDNA-positive CSF-tumor pairs and further analysis of CSF ctDNA revealed a broad spectrum of promoter mutations, copy number alterations and structural rearrangements." (PMID 31284524, 2019). "Our analysis illuminated a tumor evolutionary series of events, which included 1p/19q codeletion, IDH1 R132H, and TERT C250T as early events, followed by loss of function of NDST4 and mutations in FUBP1 and CIC as late events." (PMID 31217899, 2019). "The data indicates that there is a closer association between the loss of tumor vascular integrity than IDH1 mutational status in the appearance of CD163+ TAM." (PMID 30400835, 2018). "In our study we also proved the presence of IDH1 R132H mutation in the tumor tissue to serve as the positive prognostic factor for patients with GBM in relation to PFS as well as OS." (PMID 29662659, 2018). "The largest subgroup comprised 133 tumors (68.9%) and showed the characteristic 1p/19q co-deletion as well as IDH1 or IDH2 mutations in each tumor." (PMID 29631562, 2018). "In patient #3, the IDH1 mutation in codon 132 was confirmed in REC tumor, with a 17.37% of frequency (p = 0.0001) and PR counterpart resulted WT." (PMID 29871612, 2018). "In order to confirm the naïve IDH1 mutation identified by Sanger sequencing in REC tumor, patient #3 was analyzed by NGS using the AmpliSeq technology on Ion Torrent device." (PMID 29871612, 2018). "The differences in tumour types and the fact that these cell lines harbour an engineered instead of an endogenous IDH1/2 mutation likely explain the differences in experimental findings." (PMID 29576625, 2018). "Unfortunately, there are few in vivo model systems for IDH-mutated tumors to study the effects of IDH1 mutations in tumor development." (PMID 29953513, 2018). "An alternative approach has been opened since the discovery that all tumor relevant mutations in IDH1 and IDH2 result in a neomorphic enzyme activity ultimately leading to a dramatic increase of intracellular 2HG." (PMID 29499756, 2018).